FAM185A (family with sequence similarity 185 member A)
Synonyms: MGC35361
Tractability: No criterion of Open Targets' tractability assessment is met for any kind of drug.
Gene: Protein-coding gene on chromosome 7 (102,748,969 to 102,809,552, forward strand). Ensembl gene ENSG00000222011.
Subcellular location (Human Protein Atlas): Cytosol
Gene Ontology:
Molecular function: protein binding
Cellular component: mitochondrion
Genetic constraint (gnomAD): Loss-of-function variants: 17 observed, 28.03 expected, observed/expected ratio (o/e) 0.61, 90% interval 0.41 to 0.91. The synonymous counts are far from expectation, so gnomAD's model fits this gene poorly and the ratio says little. Missense variants: 246 observed, 358.8 expected, observed/expected ratio (o/e) 0.69, 90% interval 0.62 to 0.76. Synonymous variants: 96 observed, 145.66 expected, observed/expected ratio (o/e) 0.66, 90% interval 0.56 to 0.78.
Homologues: Orthologues: chimpanzee FAM185A (99% identical), macaque FAM185A (93% identical), rabbit FAM185A (75% identical), pig FAM185A (75% identical), dog FAM185A (71% identical), mouse Fam185a (71% identical), guinea pig FAM185A (69% identical), rat AABR07059232.1 (69% identical), tropical clawed frog fam185a (45% identical), zebrafish fam185a (34% identical), Drosophila melanogaster CG8187 (19% identical).